SKI (SKI proto-oncogene)
Description:
May play a role in terminal differentiation of skeletal muscle cells but not in the determination of cells to the myogenic lineage. Functions as a repressor of TGF-beta signaling.
Synonyms: SGS; SKV
Tractability: PROTAC: UniProt records ubiquitination sites on it; ubiquitination databases record sites on it.
Gene: Protein-coding gene on chromosome 1 (2,227,388 to 2,310,213, forward strand). Ensembl gene ENSG00000157933.
Subcellular location: Nucleus
Subcellular location (Human Protein Atlas): Nucleoplasm; Golgi apparatus; Nuclear bodies
Pathways (Reactome):
Signal Transduction: Downregulation of SMAD2/3:SMAD4 transcriptional activity; Signaling by BMP
Gene Ontology:
Molecular function: DNA-binding transcription factor binding; DNA-binding transcription repressor activity, RNA polymerase II-specific; identical protein binding; protein binding; protein domain specific binding; protein kinase binding; SMAD binding; ubiquitin protein ligase binding; zinc ion binding; DNA-binding transcription factor activity, RNA polymerase II-specific; histone deacetylase inhibitor activity; RNA polymerase II cis-regulatory region sequence-specific DNA binding
Biological process: myotube differentiation; negative regulation of activin receptor signaling pathway; negative regulation of BMP signaling pathway; negative regulation of cell population proliferation; negative regulation of osteoblast differentiation; negative regulation of Schwann cell proliferation; negative regulation of SMAD protein signal transduction; negative regulation of transcription by RNA polymerase II; negative regulation of transforming growth factor beta receptor signaling pathway; positive regulation of DNA binding; anterior/posterior axis specification; bone morphogenesis; camera-type eye development; camera-type eye morphogenesis; cell motility; embryonic limb morphogenesis; face morphogenesis; lens morphogenesis in camera-type eye; myelination in peripheral nervous system; negative regulation of fibroblast proliferation; neural tube closure; nose morphogenesis; olfactory bulb development; positive regulation of transcription by RNA polymerase II; positive regulation of Wnt signaling pathway; and 8 more
Cellular component: centrosome; nuclear body; nucleoplasm; nucleus; PML body; protein-containing complex; cytoplasm; transcription regulator complex; transcription repressor complex
Genetic constraint (gnomAD): Loss-of-function variants: 29 observed, 48.9 expected, observed/expected ratio (o/e) 0.59, 90% interval 0.44 to 0.81. The synonymous counts are far from expectation, so gnomAD's model fits this gene poorly and the ratio says little. Missense variants: 1,017 observed, 919.36 expected, observed/expected ratio (o/e) 1.11, 90% interval 1.05 to 1.16. Synonymous variants: 673 observed, 449.7 expected, observed/expected ratio (o/e) 1.5, 90% interval 1.4 to 1.6.
Gene-disease validity (ClinGen):
ClinGen rates the evidence that SKI causes each of these diseases.
Shprintzen-Goldberg syndrome (autosomal dominant): Definitive.
Homologues: Orthologues: macaque SKI (99% identical), chimpanzee SKI (99% identical), dog SKI (94% identical), rat Ski (94% identical), mouse Ski (93% identical), pig SKI (93% identical), guinea pig SKI (75% identical), tropical clawed frog ski (75% identical), zebrafish skia (69% identical). Paralogues in human: SKIL (36% identical), SKOR1 (23% identical), SKOR2 (22% identical).
Diseases named in the same sentence as SKI in open-access papers:
SKI is named in the same sentence as 61 diseases in open-access papers, as found by Europe PMC text mining. Sharing a sentence is not in itself a finding about the gene and the disease. The quoted sentences say what the papers report.
melanoma (9 papers, 2009 to 2023). A malignant, usually aggressive tumor composed of atypical, neoplastic melanocytes. "MiR-155, by targeting SKI mRNA and downregulating SKI mRNA translation, also blocks the proliferation of melanoma cells." (PMID 36982460, 2023). "Another relevant target identified was SKI protein, which is a transcriptional coregulator highly expressed in melanoma." (PMID 37175874, 2023). "SKI thus helps to maintain the MITF homeostasis downstream of BRAFV600E required for BRAF-driven melanoma development." (PMID 26977879, 2016). "This suggested a link between MEK and the transcriptional co-suppressor SKI, and indeed BRAF or MEK inhibition reduced SKI protein and mRNA levels in melanoma cells." (PMID 26977879, 2016). "The suppressor function of SKI is maintained in melanoma, where its overexpression led to a reduction and its depletion to an increase in PAX3 and MITF expression." (PMID 26977879, 2016). "Remarkably, it has been reported that melanoma cells express high amounts of SKI protein, which localizes both in the nucleus and in the cytoplasm." (PMID 21211030, 2011). "In view of these experiments, it appears that despite high expression of the SKI protein, melanoma cells exhibit a strong transcriptional response to exogenous TGF-β." (PMID 21211030, 2011). "While understanding the exact role played by labile c-SKI protein in melanoma remains to be understood, we believe that targeting SKI to prevent tumor spreading and disease progression is likely not an appropriate therapeutic strategy." (PMID 21211030, 2011). "Consistent with its role as an oncogene, SKI expression is increased in different cancer types, including esophageal squamous cell carcinoma, melanoma, and acute myeloid leukemias." (PMID 22194822, 2011). "The human SKI gene is located at chromosome 1p36, a potential tumor suppressor locus that is frequently deleted in various human cancers including neuroblastoma, melanoma, colorectal carcinoma and leukemia." (PMID 21211030, 2011). "MG132 treatment of 1205Lu melanoma cells treated resulted in increased SKI protein content, consistent with a role of the proteasome in controlling SKI protein levels, both in normal and malignant melanocytes." (PMID 21211030, 2011). "We report that despite high levels of SKI protein expression, melanoma cells exhibit strong transcriptional responses to TGF-β." (PMID 21211030, 2011). "In the present study, we demonstrate that autocrine TGF-β signaling is active despite high levels of SKI and SnoN protein in all melanoma cell lines that we examined, including those from our initial studies." (PMID 21211030, 2011). "Our data are consistent with those reported by Medrano and co-workers that melanoma cells in culture and human melanoma lesions exhibit high SKI protein levels." (PMID 21211030, 2011). "We identified SKI as an MAPK-regulated suppressor of PAX3 in melanoma cells." (PMID 26977879, 2016). "In melanoma cells, however, the synergistic overexpression of SKI and FHL2 enhanced cell growth." (PMID 26320172, 2015). "Consistent with a potential oncogenic role, SKI and SnoN are often expressed at high levels in various human cancers cells derived from melanoma, esophageal cancer, pancreatic cancer and leukemia, due to increased transcription, gene amplification, and/or protein stabilization." (PMID 21211030, 2011). "This study was thus initiated in order to clarify the discrepancy in the literature regarding the respective roles played by TGF-β signaling and that of potentially antagonistic SKI proteins in the control of the invasive and metastatic capacities of human melanoma cells." (PMID 21211030, 2011). "SKI is an oncoprotein that is frequently overexpressed in some types of cancer such as melanoma." (PMID 19703312, 2009). "On the other hand, all melanoma cell lines tested (WM793, 1205Lu, WM852, WM983B and SK28) expressed high levels of SKI and SnoN protein." (PMID 21211030, 2011).
melanoma (continued). "Because we had identified the SMAD2/4/SKI complex as relevant for the inhibitory action of nelfinavir on PAX3 transcription, and nelfinavir counteracted the MAPKi-induced tolerance in melanoma cells, we wanted to identify the link between the SMAD/SKI suppressor complex and MAPK signaling." (PMID 26977879, 2016). "SKI is an important regulator of melanoma growth, and the elevated MAPK-pathway activity found in melanomas might contribute to its increased expression." (PMID 26977879, 2016). "Despite high expression in melanoma cells, the role of SKI in melanoma remains elusive: SKI does not efficiently interfere with the pro-oncogenic activities of TGF-β, unless stabilized by proteasome blockade." (PMID 21211030, 2011). "SnoN may exert similar functions when SKI is not expressed in some melanoma cell lines." (PMID 21211030, 2011). "It has been suggested that such high expression of SKI blocks TGF-β transcriptional responses, in particular the induction of p21/WAF, resulting in an inactive TGF-β pathway in melanoma cells and lack of growth inhibitory activity of TGF-β." (PMID 21211030, 2011). "Also, SKI knockdown did not alter the capacity of 1205Lu and WM852 (not shown) melanoma cells to invade MatrigelTM." (PMID 21211030, 2011). "Noteworthy, when we initially reported that autocrine SMAD signaling occurs in melanoma cells and is dependent upon secretion and pericellular activation of TGF-β, we did not know the expression status of SKI and SnoN protein in the various cell lines used in our studies." (PMID 21211030, 2011).
breast carcinoma (7 papers, 2019 to 2025). "This translocation was found to generate a gene fusion between SKI-NMT1 genes, SKI is an interesting gene reported both with a pro-oncogenic and a suppressor tumor activity in breast cancer models." (PMID 39239354, 2024). "For example, Transcriptional activity of SMAD2/SMAD3:SMAD4 heterotrimer involved in the degradation of SKI/SKIL, thus causing malignant transformation in breast cancer." (PMID 38652712, 2024). "Genes MIR124-2, PBX1, SKI, GHSR and RBPMS were reported to be associated with breast cancer, and a gene CYP19A1 was reported to be be associated with endometrial cancer." (PMID 31640538, 2019). "Even though their time-dependent effects have not been characterized in detail, SKIL and SKI are known to be repressors of the TGFβ-induced gene expression response, which control EMT in non-small cell lung cancer and metastasis in breast cancer cells." (PMID 39542693, 2025).
acute myeloid leukemia (3 papers, 2011 to 2022). Acute myeloid leukemia (AML) is a group of neoplasms arising from precursor cells committed to the myeloid cell-line differentiation. "In acute myeloid leukemia (AML), LINC00467 upregulated oncogene SKI expression by sponging miR-339." (PMID 36203193, 2022).
cardiomyopathy (3 papers, 2014 to 2025). A disease of the heart muscle or myocardium proper. "In the literature from 22 to 27% of patients presented cardiomyopathy and two critical regions for cardiomyopathy have been described one of which includes PRKCZ, SKI, and PRDM16." (PMID 36369750, 2023).
craniosynostosis (3 papers, 2016 to 2022). Craniosynostosis is defined as the premature fusion of one or more cranial sutures leading to secondary distortion of skull shape resulting in skull deformities with a variable presentation. "This frequency is much greater than any other genotype causing syndromic midline craniosynostosis (e.g., TGFBR1/2, SKI, RUNX2), which are sufficiently rare that their prevalence has not been well-established." (PMID 27606499, 2016). "Mutations in the SKI gene encoding the SKI proto-oncogene protein cause SGS, which is characterized by severe marfanoid habitus, camptodactyly, typical facial dysmorphism, craniosynostosis, and mild/moderate intellectual disability." (PMID 30037098, 2018).
gastric cancer (3 papers, 2019 to 2024). A primary or metastatic malignant neoplasm involving the stomach. "Previously, MEL1/PRDM16, together with SKI, was aberrantly expressed by chromosomal co-amplification of 1p36.32 in gastric cancer cells." (PMID 32290321, 2020).
Shprintzen-Goldberg syndrome (3 papers, 2015 to 2022). Shprintzen-Goldberg syndrome (SGS) is a very rare genetic disorder characterized by craniosynostosis, craniofacial and skeletal abnormalities, marfanoid habitus, cardiac anomalies, neurological abnormalities, and intellectual disability. "The SKI mutation was also associated with Shprintzen-Goldberg syndrome with distinctive facial features, hypotonia, and intellectual deficiency." (PMID 33732167, 2021).
brain tumor (2 papers, 2023 to 2025). "It specifically interacts with transforming growth factor β (TGF-β) pathway protein SMAD3 and Ski proto-oncogene (SKI) to help maintain the tumorigenicity of brain tumor stem cells (BTSCs) both in vitro and situ xenograft models." (PMID 40450300, 2025).
esophageal squamous cell carcinoma (2 papers, 2011 to 2019). Esophageal squamous cell carcinoma (ESCC) is a type of esophageal carcinoma (EC) that can affect any part of the esophagus, but is usually located in the upper or middle third. "On a similar note, the SKI oncogene has been linked to several HPV-associated cancers such as esophageal squamous cell carcinoma and cervical cancer." (PMID 31569353, 2019).
experimental autoimmune encephalomyelitis (2 papers, 2021). An autoimmune demyelinating disease of the central nervous system that is produced experimentally in animals by the injection of homogenized brain or spinal cord in Freund's adjuvant. "Besides, SKI (rs61776614) inhibited pathogenic Th17 cell response and ameliorated experimental autoimmune encephalomyelitis." (PMID 35211151, 2021). "Functionally, using a knock-in mouse model, we found ectopic SKI expression specifically in T cells prevented myelin oligodendrocyte glycoprotein peptide (MOG33–55) induced experimental autoimmune encephalomyelitis (EAE), an animal model of human multiple sclerosis." (PMID 34335622, 2021).
leukemia (2 papers, 2011 to 2018). A malignant (clonal) hematologic disorder, involving hematopoietic stem cells and characterized by the presence of primitive or atypical myeloid or lymphoid cells in the bone marrow and the blood. "MYB and SKI both are overexpressed or mutated in different tumors and leukemia subtypes." (PMID 29854289, 2018). "Although SKI function is well characterized, the transcriptional regulation of the SKI gene itself is still enigmatic, in particular in leukemia and other tumor entities with high SKI expression levels but no chromosome 7 deletion." (PMID 29854289, 2018). "Besides its normal cellular role SKI is upregulated in different solid tumors and leukemias." (PMID 29854289, 2018).
myeloproliferative disease (2 papers, 2018 to 2024). "Although SKI is more widely expressed than SnoN in mature haematopoietic cells and plays crucial roles in haematopoiesis and myeloproliferative diseases, its roles in differentiation and functions of immune cells remained largely undetermined." (PMID 38960622, 2024). "In contrast, overexpression of SKI results in a chronic neutrophilic leukemia (CNL)-resembling myeloproliferative disease in mice." (PMID 29854289, 2018).
pancreatic cancer (2 papers, 2020 to 2023). "SKI is known to promote pancreatic cancer cell proliferation and SKI overexpression is significantly associated with a decreased patients’ survival time." (PMID 33023028, 2020). "In conclusion, the combination of HDACi with NK cell-based immunotherapy is an attractive treatment option for pancreatic tumors, specifically for patients with high SKI protein levels to overcome SKI-mediated immune evasion." (PMID 33023028, 2020).
atherosclerosis (1 paper, 2022). A disease characterized by the build-up of fatty material and calcium deposition in the arterial wall resulting in partial or complete occlusion of the arterial lumen. "Exploration the role of miR552/SKI axis in VSMCs proliferation may have broad prospects for clinical combined intervention of atherosclerosis." (PMID 35857794, 2022). "SKI, one of the miR-552 target genes identified in the present study, has been reported to play a protective role in VSMC against atherosclerosis." (PMID 35857794, 2022).
autism (1 paper, 2021). Persistent deficits in social interaction and communication and interaction as well as a markedly restricted repertoire of activity and interest as well as repetitive patterns of behavior. "TNRC6B, PTEN, AGO1, SKI, and SMAD4 were the most frequent targets, and miR-92a-3p had the most target autism risk genes." (PMID 34744804, 2021).
autoimmune disease (1 paper, 2021). A disorder resulting from loss of function or tissue destruction of an organ or multiple organs, arising from humoral or cellular immune responses of the individual to their own tissue constituents. "Our study reveals a critical role of SKI in regulating pathogenic Th17 cells and related autoimmune disease." (PMID 34335622, 2021).
cancers of the skin (1 paper, 2015). "Overexpression of either SKI or SKIL in chicken embryo fibroblasts is sufficient to induce oncogenic transformation, and SKIL expression is elevated in many human cancers, including cancers of the skin, breast, colon and blood." (PMID 25749039, 2015).
cleft lip (1 paper, 2008). Congenital defect in the upper lip where the maxillary prominence fails to merge with the merged medial nasal prominences. "The SKI proto-oncogene is a likely candidate for cleft lip/palate found in 17% of monosomy 1p36 patients." (PMID 19019217, 2008).
colorectal cancer (1 paper, 2020). A primary or metastatic malignant neoplasm that affects the colon or rectum. "Although upregulation of SKI has been reported in many cancers such as colorectal cancer, it is labeled as a tumor suppressor by many studies." (PMID 32341755, 2020).
diabetes (1 paper, 2018). "This is reflected by the increased induction of chemokine transcripts by plasma of siblings with low HLA risk and individuals with diabetes, and elevated induction of regulatory transcripts (IL2RA, CBLB, SMURF1, SMURF2, SKI) by plasma of siblings with high HLA risk and unrelated control individuals." (PMID 30167736, 2018).
dry eye (1 paper, 2025). "While these results are based on a rat corneal injury model and require confirmation in human studies, they suggest that JAK1, SKI, and ZBTB16 could represent candidate biomarkers for future diagnostic assays or targets for immunomodulatory therapy in dry eye." (PMID 40940727, 2025). "Upregulation of key mediators, such as JAK1, SKI, and ZBTB16, paralleled increased IL-6, IL-1β, and TNF-α expression, implicating innate immune activation in dry eye pathogenesis." (PMID 40940727, 2025).
esophageal adenocarcinoma (1 paper, 2017). A malignant tumor with glandular differentiation arising predominantly from Barrett mucosa in the lower third of the esophagus. "Copy number alterations were also analyzed among esophageal adenocarcinoma, which showed that SKI and PRKCZ, biomarkers involved in transforming growth factor-β pathway, were located at a deletion region, suggesting the potential utility of novel biomarkers for EA29." (PMID 28169357, 2017).
Harel-Yoon syndrome (1 paper, 2022). A syndromic neurodevelopmental disorder characterized by delayed psychomotor development, intellectual disability, truncal hypotonia, spasticity, and peripheral neuropathy. "Referring to the following databases: Berry DB, DECIPHER, OMIM, and DGV, 1p36.33 contains multiple functional genes such as SKI, GNB1, DVL1 and ATAD3A, among which ATAD3A gene is related to Harel-Yoon syndrome, and the possible clinical phenotypes include psychomotor retardation, mental retardation." (PMID 36471261, 2022).
hemangiosarcoma (1 paper, 2024). "In our exploration of the genetic landscape of canine hemangiosarcoma, we focused on identifying copy number alterations (CNAs) within genes previously associated with the disease, including CDKN2A/B, VEGFA, KDR, SKI, MYC, and KIT." (PMID 39872607, 2024).
Hypodontia (1 paper, 2021). The absence of five or less teeth from the normal series by a failure to develop. "This novel finding would help to shed light on the regulation of SKI and FHIT on the orofacial cleft and hypodontia formation." (PMID 33732167, 2021).